SIAH2 (siah E3 ubiquitin protein ligase 2)
Diseases named in the same sentence as SIAH2 in open-access papers (continued):
Sharing a sentence is not in itself a finding about the gene and the disease.
tumor (continued). "It is of great significance to deeply understand the function of SIAH2 and DBC1 and the role of hypoxia in regulating tumorigenesis and tumor progression, which provides a solid theoretical basis for cancer treatment." (PMID 35913115, 2022). "Taken together, our study unveils the molecular mechanism of M6A-Siah2-PD-L1 axis in CAA, and extends the understanding of Siah2 in tumor-immune microenvironment and immunotherapy." (PMID 35154166, 2022). "Six genes overlapped in the three top 50 lists for tumor response, overall clinical response, and PFS, including MAGOH, C16orf87, ORC1, NAA35, PWP2, and SIAH2." (PMID 35892846, 2022). "(I) Immunohistochemical analysis of SIAH2 knockout and SIAH2/CCAR2 double-knockout xenograft tumor tissues with the indicated antibodies." (PMID 35913115, 2022). "Collectively, we identify a novel mechanism by which SIAH2 regulates DBC1 protein stability in response to hypoxic stress, contributing to tumorigenesis and tumor progression." (PMID 35913115, 2022). "To validate the effects of SIAH2-mediated DBC1 stability on tumorigenesis and tumor progression in vivo, we implanted SIAH2 knockout and SIAH2/CCAR2 double-knockout MDA-MB-231 cells into the mammary fat pads of BALB/c nude mice and then monitored tumor growth." (PMID 35913115, 2022). "Mechanistically, hypoxic stress promoted the interaction between DBC1 and SIAH2 and enhanced the disassociation of DBC1 from OTUD5, resulting in an increase in DBC1 ubiquitination and degradation, contributing to tumor cell proliferation and migration." (PMID 35913115, 2022). "However, several studies revealed that Siah2 exhibited tumor suppressor function by promoting the proteasome-mediated degradation of several oncoproteins, suggesting that Siah2 could exert its biological function depending on different stages of tumor development." (PMID 35154166, 2022). "Of interest, the four protein kinases that show negative regulation of SIAH2 (activity and/or stability), namely HIPK2, DYRK2, CHK2, and PLK3, are all considered to have tumor suppressive functions and with roles in the DNA damage response." (PMID 33842469, 2021). "In contrast, the two kinases that positively regulates SIAH2, namely p38 and SRC, both have well-established tumor promoting functions." (PMID 33842469, 2021). "Phosphorylation by SRC activates SIAH2, which is necessary and sufficient for SRC-mediated degradation of CCAAAT/enhancer binding protein delta (C/EBPδ), a protein with tumor suppressive function." (PMID 33842469, 2021). "For instance, hypoxia induces E3 ubiquitin ligase SIAH2 mediated ubiquitination and proteolysis of α-KGDH, inhibiting glutamine oxidation and promoting glutamine-dependent lipid synthesis to promote tumor growth." (PMID 33004065, 2020). "Expression level of seven in absentia homolog 2 (SIAH2), an E3 ubiquitin-protein ligase, is upregulated in NSCLC and correlated with tumor grade." (PMID 28210267, 2017). "In a hypoxic environment, HIPK2 down-regulates the activity of HIF-1, Siah1, Siah2, VEGF and WBS-1 to inhibit tumor angiogenesis." (PMID 28107201, 2017). "Correlation of SIAH2 and DBC1 expression with tumor progression in BRCA." (PMID 35913115, 2022). "Additionally, knockout of SIAH2 promoted apoptosis and reduced cell migration and tumor proliferation, whereas double knockout of CCAR2 and SIAH2 partially rescued cell proliferation and tumorigenesis." (PMID 35913115, 2022). "The staining revealed that Siah2 was expressed within the tumor but not in neighboring untransformed cerebellar tissue." (PMID 33082319, 2020). "In this work, we present step two by showing that under pathophysiological conditions, such as hypoxia microenvironment, not only the activity of Siah2 is elevated, but also the secretion of TGF-β, a growth factor that has complicated function in tumour development." (PMID 27030211, 2016).
tumor (continued). "SIAH2 was shown to lead to LATS2 destabilization and YAP activation in hypoxic cells, an effect that provides a tentative connection between ATF4 and HIPPO pathway in stressed cells in the tumor microenvironment." (PMID 27409837, 2016). "The SIAH2-dependent proteasomal degradation of TYK2 we report here might represent a possibility to reduce aberrant STAT3 signaling and tumor progression." (PMID 24833526, 2014). "Notably, HIF activates downstream glycolytic enzymes, while SIAH2 enhances the Warburg effect by ubiquitinating the downstream molecule nuclear respiratory factor 1 (NRF1) and facilitating metabolic reprogramming, thereby ensuring active tumor cell metabolism." (PMID 39227970, 2024). "Interestingly, we further confirmed that SIAH2 and OTUD5 competitively bind to DBC1 at the same N-terminal region, and hypoxia promotes the interaction of DBC1 with SIAH2 rather than OTUD5, resulting in ubiquitination and degradation of DBC1 to promote tumor progression." (PMID 35913115, 2022). "The difference analysis of 41 paired samples of TCGA-COAD showed that the mRNA levels of ARHGAP4, SIAH2, TRIM45, and WDR72 were significantly upregulated in the tumor group, while MID2 and UBE2D2 showed no statistical difference." (PMID 39268080, 2024). "We confirmed a negative correlation between Siah2 and PD-L1 protein level, a negative correlation between METL14 and Siah2, and a positive correlation between METL14 and PD-L1 in 30 human CCA tumor tissues by Western blot." (PMID 35154166, 2022). "In univariate analyses, lymph node positivity, surgical margin positivity, non-localized tumor, age at prostatectomy, and biomarkers CCND1, HMMR, IGF1, MKI67, SIAH2, and SMAD4 in malignant epithelium were significantly associated with time to BF." (PMID 24708576, 2014). "The seven in absentia homolog 2 (SIAH2)/with-no-lysine kinase 1 (WNK1) signaling axis has emerged as a potential regulator of these processes, yet its functional role in CRC metabolism and tumor-stroma crosstalk remains incompletely understood." (PMID 41596707, 2026). "Moreover, many genes (PTN, SIAH2, FAM111B, TMEM43, FOSL2, TRIB1 and SPATA1) were hypomethylated regardless of tumor grade." (PMID 36850002, 2023). "Inhibition of SIAH2 activity through a RING mutant, dominant-negative form of SIAH2 reduced tumorigenesis, whereas blockade of SIAH2-substrate binding site reduced metastasis but did not have an impact on tumor formation." (PMID 26580787, 2015).
cancer (41 papers, 2011 to 2025). A tumor composed of atypical neoplastic, often pleomorphic cells that invade other tissues. "Interestingly, both subsets of genes were significantly linked to female-specific cancers, supporting the ideas that the downstream enhancer of SIAH2 is both hormone-responsive, and is capable of influencing the expression of a host of genes involved in these processes." (PMID 27634217, 2016). "METTL14 enhanced m6A methylation on the seven in absentia homolog 2 (Siah2) ubiquitin ligase which is responsible for proteasomal degradation of PD‐L1 in cancer cells." (PMID 39661414, 2024). "Many of these genes, such as VIM, FOSL2, PTN, GPR3, SIAH2, UPP1, S100A2 are associated with cell migration and epithelial-mesenchymal transition (EMT) in several cancers." (PMID 36850002, 2023). "Consistent with our data, elevated SIAH2 expression has been reported in drug-resistant cancer cell lines and malignant tissues compared to healthy tissues." (PMID 36846090, 2022). "A more complete evaluation of the role of SIAH2 or ZFP521 in the DDLPS phenotype is limited by the availability of fresh tissues from these rare cancers." (PMID 35313831, 2022). "HPA analysis showed that the protein levels of LDHA and TES were highly upregulated in cancer tissues compared to normal pancreatic tissue, while those of NDST1, ANKZF1, and SIAH2 were significantly decreased in cancer tissues." (PMID 35935823, 2022). "METTL14 can induce the expression of seven in absentia homolog 2 (Siah2), which has been involved in tumorigenesis and cancer progression." (PMID 35813486, 2022). "SIAH2 protein contributes to the progression of various malignant tumors, including breast carcinoma, lung and prostate tumors, and oral cancer." (PMID 35582023, 2021). "Several studies have shown that Siah2 has important roles in tumorigenesis and metastasis in multiple cancers, including breast cancer, lung cancer, pancreatic cancer, melanoma, and PCa." (PMID 33937036, 2021). "The role of SIAH2 in HIF-1 and Ras signaling positions SIAH2 as a potentially high-value target for cancer therapy." (PMID 33842469, 2021). "Although continuing effort has identified a number of SIAH2 inhibitors, the therapeutic values of these inhibitors in cancer therapy remain to be evaluated in depth." (PMID 33842469, 2021). "Additional work will be conducted to examine the interplay between SIAH3 and SIAH1/SIAH2 in oncogenic K-RAS-driven human cancers in the future." (PMID 28784114, 2017). "This idea is supported by several previous studies that demonstrated that the RING domain-deleted SIAH1 or SIAH2 mutants (termed SIAH1/2 dominant-negative) functionally ablated endogenous activity of SIAH1 and SIAH2 in cancer biology." (PMID 28784114, 2017). "The different function of Siah1 and Siah2 in cancer is likely due to the ubiquitination of distinct substrates." (PMID 25202994, 2014). "The different roles of Siah1 and Siah2 in cancer are likely mediated through the ubiquitination of distinct substrates." (PMID 25202994, 2014). "Given the different roles of Siah1 and Siah2 in cancer and their different cellular functions, it is important to understand the structural basis of their substrate specificity and to design Siah2 specific inhibitors." (PMID 25202994, 2014). "The Siah1 and Siah2 E3 ubiquitin ligases play an important role in diverse signaling pathways and have been shown to be deregulated in cancer." (PMID 25202994, 2014). "Growing evidence highlights the functional role of Siah2 in promoting the progression of multiple types of cancer, including breast, lung, pancreatic, prostate, liver cancer and melanoma." (PMID 25202994, 2014). "Evidence from in vitro, in vivo, and patient sample studies describe opposite roles for Siah1 and Siah2 in cancer progression, metastasis, and therapeutic responses." (PMID 25202994, 2014).
cancer (continued). "The data presented here define POSH and Siah2 as important mediators of death receptor mediated apoptosis and suggest targeting the interaction of these two E3 ligases is a promising novel cancer therapeutic strategy." (PMID 21586138, 2011). "It remains to be tested if targeting of the extrinsic apoptotic pathway via Siah2 or POSH inhibition in combination with current intrinsic targeting compounds is a promising cancer therapeutic strategy." (PMID 21586138, 2011). "SIAH3 appears to be an attractive target for further investigation as its active homologs, SIAH1 and SIAH2, are known to be downstream effectors of the KRAS pathway and have been shown to be associated with cancer progression and poor prognosis in multiple cancers." (PMID 40243415, 2025). "Additionally, SIAH2 has been proposed to be involved in the regulation of cancer stem cells and in orchestrating the response to hypoxia." (PMID 39268080, 2024). "Decreased p62 levels under hypoxia in the Nrf2/Siah2- and Parkin/Hsc70-dependent pathways are of interest because the suppression of p62 is critical for cancer cell survival under hypoxia and, thus, may serve as a novel target for solid tumors." (PMID 36481701, 2022). "In particular, Siah2 plays a critical role in tumorigenesis and cancer progression." (PMID 35154166, 2022). "Siah2 is known to play an important role in tumorigenesis and cancer progression." (PMID 35154166, 2022). "Future cross-cancer studies would help us determine whether Siah2 phosphorylation is essential for carcinogenic processes." (PMID 33536006, 2021). "It is conceivable that inhibition of SIAH2 and/or the kinases that regulate SIAH2 may change the response of cancer cells to the hypoxic condition, thereby altering the trajectory of cancer progression." (PMID 33842469, 2021). "Given the role of SIAH2 in the hypoxic response and cancer, this E3 ubiquitin ligase and its kinase regulators may be targeted for cancer therapy." (PMID 33842469, 2021). "The evidence that hypoxia-induced SIAH2 stimulates transcriptional activity of YAP suggests that the hypoxic microenvironment in solid tumors might contribute to support cancer cell growth by inhibiting Hippo pathway activity." (PMID 29673168, 2018). "The recently developed covalent SIAH2 inhibitors, BI-107F7 and BI-107F9, which act by disrupting the interaction between SIAH2 and its substrates, might serve as chemical probes for assessing the role of SIAH2 inhibition for cancer therapy." (PMID 29673168, 2018). "This may indicate that SIAH2-mediated regulation of LATS2 turnover may play an important role in this cancer." (PMID 29673168, 2018). "By taking advantage of nonfunctional SIAH3 as a putative endogenous SIAH inhibitor, we may be able to develop a novel anti-SIAH1 and anti-SIAH2 strategy by utilizing SIAH3 expression to antagonize oncogenic K-RAS-driven metastatic human cancer cells." (PMID 28784114, 2017). "Although its role in CRC remains unclear, Siah2 has been suggested to promote invasion and metastasis in a variety of other cancers, including prostate, breast and liver." (PMID 27092172, 2016). "Together, these data suggest a possible scenario in which Siah2 targeting of HIPK2 protects cancer cells from apoptosis induction while inhibition of Siah2 could increase HIPK2 abundance thus sensitizing cancer cells to cell death agents." (PMID 21586138, 2011). "Additionally, some other studies have pointed out that SIAH2 also has certain anti-cancer effects." (PMID 39981438, 2025). "SIAH2 may be reversely regulated by E2 and EGF, thereby causing drug resistance in cancer." (PMID 35582023, 2021). "This provides evidence that SIAH2 may facilitate negative regulation of NEMG expression in cancer." (PMID 30833558, 2019). "A further mechanism in basal-like cancer may also involve p38 mitogen-activated protein kinase, which is also upregulated in the basal-like phenotype, as activated p38 increases the activity of SIAH2." (PMID 21306611, 2011).
cancer (continued). "Considering these findings, further research is urgently needed to elucidate the roles of ARIH1, SIAH2, UBR5, and WWP2 in modulating mitophagy, mitochondrial homeostasis, and drug resistance in cancer." (PMID 40004017, 2025). "SIAH2 is a RING E3 ubiquitin ligase, and its overexpression plays a vital role in tumorigenesis and cancer progression." (PMID 39981438, 2025). "Seven in absentia homolog 2 (Siah2), a RING E3 ubiquitin ligase, plays a vital role in tumorigenesis and cancer progression." (PMID 39802639, 2025). "It has been reported that PERK/ATF4 induces transcription and expression of the ubiquitin ligases SIAH1/2 in cancer cell lines.To identify the link among PERK, ATF4, SIAH2 and HIPK2, knockdown of genes by siRNA was carried out." (PMID 37268944, 2023). "Taken together, our results evidenced a new regulatory mechanism of Siah2 by METTL14-induced mRNA epigenetic modification and the potential role of Siah2 in cancer immunotherapy." (PMID 35154166, 2022). "Overexpression of SIAH2 increases H3K27 acetylation at c-MYC–controlled genes, increases metabolic output, and accelerates cancer cell proliferation." (PMID 36846090, 2022). "In this review, we will discuss the regulation of the SIAH2-HIF-1 axis via phosphorylation of SIAH2 by these kinases and the potential implication of this regulation in cancer biology and cancer therapy." (PMID 33842469, 2021). "In this review, we will discuss the regulation of the SIAH2-HIF-1 pathway by protein kinases and its potential implications in cancer biology and therapy." (PMID 33842469, 2021). "Our decision was bolstered by data from the Pediatric Cancer Genome Project (PCGP), which revealed that in human MBs, a group of tumors that arise from GNPs33, the expression of Siah2 transcripts was highest in the Shh subgroup of the tumors." (PMID 33082319, 2020). "Thus, HDAC3 may confer sensitivity to anti-cancer drugs by regulating expression of SIAH2." (PMID 30583572, 2018). "We find that SIAH1 and SIAH2 are expressed in all human epithelial cell lines examined thus far, while SIAH3 is only expressed in a limited subset of cancer cell lines." (PMID 28784114, 2017). "In addition, seven in absentia homolog 2 (Siah2), a RING E3 ubiquitin ligase, has been involved in tumorigenesis and cancer progression." (PMID 35154166, 2022). "Previous literature has identified hypoxia as a regulator of both isocitrate dehydrogenase and SIAH2 in several types of cancer, although this work has not been studied specifically in models of cancer progression." (PMID 35847893, 2022). "Together, these data suggest that development of second generation proteasome inhibitors that block E3 ubiquitin ligases, such as Siah2 and POSH, could be beneficial for cancer treatment." (PMID 21586138, 2011). "DHX15 play key role in cancer progression through activating AR activity through Siah2-mediated ubiquitination independent of its ATPase activity, but this gene might be liable for development of pituitary prolactinoma." (PMID 33709028, 2021). "As Siah2 and POSH suppress cell death, their upregulation may be advantageous in cancer cells." (PMID 21586138, 2011).
adenocarcinoma (2 papers, 2014 to 2017). A common cancer characterized by the presence of malignant glandular cells. "This implies that the protein expression of SIAH2 is significantly upregulated in adenocarcinoma." (PMID 28210267, 2017).
metabolic disease (2 papers, 2016 to 2022). A congenital disorder (due to inherited enzyme abnormality) or acquired (due to failure of a metabolically important organ) disorder resulting from an abnormal metabolic process. "We describe the relationship between the corepressor NCoR1 and its E3 ubiquitin ligase Siah2 and the potential of manipulating their mutual regulation to treat metabolic diseases." (PMID 26832397, 2016). "In conclusion, these observations suggest that the Siah2/NCoR1 axis may be an attractive target for the treatment of metabolic diseases and several types of cancers." (PMID 26832397, 2016).
infection (1 paper, 2021). The state of being infected such as from the introduction of a foreign agent such as serum, vaccine, antigenic substance or organism. "Acetylation of Siah2 promotes Siah2 stabilization in GECs infected with H. pylori and induces Siah2-mediated prolyl hydroxylase 3 degradation, thus contributing to infection-induced hypoxia." (PMID 33536006, 2021). "In the case of phospho-null mutant T279A-expressing cells, the increase in phosphorylation post-infection was lesser than the WT and T275A-infected cells indicating that Thr279 was the prime site for Siah2 phosphorylation in infected GECs." (PMID 33536006, 2021). "Our group identified that Siah2 was optimally induced by H. pylori 12 h after infection and at 200 MOI." (PMID 33536006, 2021). "From the western blot results, enhanced Siah2 level as well as increase in P-Ser-Siah2 and P-Thr-Siah2 were noticed in H. pylori-infected cells, reaching optimal levels at 12 h post infection." (PMID 33536006, 2021). "Western blotting and graphical presentation with statistical analysis confirmed that P-Ser-Siah2, P-Thr-Siah2 increased significantly along with Siah2 after mrckβ overexpression and 12 h H. pylori-infection, but not at 6 h, when Siah2 did not yet reach its optimal level." (PMID 33536006, 2021).